SCUBE3 (signal peptide, CUB domain and EGF like domain containing 3)
Description:
Is a positive regulator of the BMP signaling pathway, required for proper chondrogenesis, osteogenesis and skeletal development. It acts as a coreceptor for BMP ligands, particularly BMP2 and BMP4, facilitating their interactions with BMP type I receptors. It is required for ligand-induced recruitment of BMP receptors to lipid rafts (By similarity). Binds to TGFBR2 and activates TGFB signaling. In lung cancer cells, could serve as an endogenous autocrine and paracrine ligand of TGFBR2, which could regulate TGFBR2 signaling and hence modulate epithelial-mesenchymal transition and cancer progression.
Synonyms: CEGF3; FLJ34743; SSFSC2
Tractability: Antibody: UniProt places it where antibodies can reach, with high confidence; its Gene Ontology location is reachable by antibodies, with high confidence; UniProt predicts a signal peptide or a membrane-spanning region; the Human Protein Atlas places it where antibodies can reach.
Gene: Protein-coding gene on chromosome 6 (35,213,859 to 35,253,080, forward strand). Ensembl gene ENSG00000146197.
Subcellular location: Secreted; Cell surface
Subcellular location (Human Protein Atlas): Plasma membrane; Predicted to be secreted
Pathways (Reactome):
Extracellular matrix organization: Degradation of the extracellular matrix
Gene Ontology:
Molecular function: BMP binding; BMP receptor binding; identical protein binding; protein binding; calcium ion binding
Biological process: positive regulation of BMP signaling pathway; positive regulation of osteoblast differentiation; signal transduction; positive regulation of signal transduction
Cellular component: cell surface; extracellular region; plasma membrane
Genetic constraint (gnomAD): Loss-of-function variants: 30 observed, 101.16 expected, observed/expected ratio (o/e) 0.3, 90% interval 0.22 to 0.4. The upper end of that interval is the gene's LOEUF score, 0.4, which puts it in group 1 of 6, group 1 being the genes least tolerant of losing a copy. Missense variants: 940 observed, 1,249.1 expected, observed/expected ratio (o/e) 0.75, 90% interval 0.71 to 0.79. Synonymous variants: 403 observed, 468.52 expected, observed/expected ratio (o/e) 0.86, 90% interval 0.79 to 0.93.
Homologues: Orthologues: chimpanzee SCUBE3 (100% identical), macaque SCUBE3 (99% identical), dog SCUBE3 (97% identical), pig SCUBE3 (96% identical), mouse Scube3 (96% identical), rat Scube3 (96% identical), rabbit SCUBE3 (95% identical), guinea pig SCUBE3 (94% identical), zebrafish scube3 (70% identical). Paralogues in human: SCUBE1 (66% identical), SCUBE2 (61% identical).
Diseases named in the same sentence as SCUBE3 in open-access papers:
SCUBE3 is named in the same sentence as 43 diseases in open-access papers, as found by Europe PMC text mining. Sharing a sentence is not in itself a finding about the gene and the disease. The quoted sentences say what the papers report.
lung carcinoma (14 papers, 2013 to 2025). "Former studies have shown that the knockdown of SCUBE3 suppressed lung cancer invasion and metastasis and breast cancer cell growth, invasion, and migration." (PMID 37189178, 2023). "In tumours, SCUBE3 not only mediates the angiogenesis of lung cancer and promotes metastasis and invasion by promoting epithelial-mesenchymal transformation but also promotes the proliferation of osteosarcoma cells and influences the prognosis of patients." (PMID 34980127, 2022). "In the salmon module, the hub Scube3 is a TGF-β receptor ligand that induces EMT in lung cancer, whereas Ctnnal1 (catenin alpha-like 1) inhibits EMT in bronchial epithelial cells by reducing TGF-β levels." (PMID 32831131, 2020). "In a similar way, KRT18_SCUBE3 and KRT18_RBM5 were found as potential prognostic gene pairs for lung cancer." (PMID 31856825, 2019). "We also investigated the genes in the prognostic gene pairs KRT18_SCUBE3 and KRT18_RBM5 for lung cancer." (PMID 31856825, 2019). "In osteosarcoma and lung cancer, SCUBE3 was highly expressed, and knockdown of SCUBE3 could inhibit the proliferation of cancer cells." (PMID 32764572, 2020). "SCUBE3 is also involved in angiogenesis and is strongly expressed in aggressive lung carcinomas." (PMID 24084050, 2013). "SCUBE3 regulates the transcriptional and translational expression of the TGF-β/Smad2/3 signaling pathway responsible for the increased invasion of lung-cancer cells." (PMID 36142489, 2022). "Microarray analysis revealed that SCUBE3 knockdown lowers the expression of genes controlling EMT and early angiogenesis in lung carcinoma." (PMID 36142489, 2022). "SCUBE3 was reported to modulate cancer progression by binding to TGFBR2 and activating TGFB signaling in human lung cancer cells." (PMID 30093865, 2018). "These included genes such as SCUBE3, MARCKSL1 and PGK1 in lung cancer, SOX4 and GNAS in breast cancer and hepatocellular carcinoma, HEG1 in hepatocellular carcinoma, PLS3 in pancreatic adenocarcinoma, FBN1 and SPARC in gastric cancer and CST1 in gastric cancer and breast cancer." (PMID 40430098, 2025). "In line with the pathological role of the SCUBE3-TGF-β signaling axis, our collaborative studies showed that soluble SCUBE3 can act via TGF-β to stimulate negative outcomes in lung cancer cells." (PMID 37237303, 2023).
breast carcinoma (10 papers, 2020 to 2025). "A recent study demonstrated an association between increased SCUBE3 expression and low E-cadherin levels in high-histological-grade breast cancer, conforming a significant role of SCUBE3 in cancer progression and poor prognosis." (PMID 36142489, 2022). "High SCUBE3 expression is associated with a significantly increased risk of death for breast cancer patients (HR: 2.77, 95% CI 1.32–5.80, p = 0.0070)." (PMID 34006286, 2021). "To better understand the relevance and underlying mechanisms of SCUBE3 expression in breast cancer, we summarized the distribution of clinicopathological information of patients in SCUBE3 high expression group and SCUBE3 low expression group." (PMID 34006286, 2021). "To explore the potential mechanism of SCUBE3 in breast cancer, we analyzed the functional protein association network." (PMID 34006286, 2021). "Taken together, these findings indicate that SCUBE3 may be an independent prognostic indicator of mortality risk in patients with breast cancer." (PMID 34006286, 2021). "Taken together, these findings suggest high expression of SCUBE3 in breast cancer was associated with poor prognosis and may be a prognostic indicator of mortality risk in breast cancer patients." (PMID 34006286, 2021). "Taken together, SCUBE3 expression was significantly different in ER, and PR, suggesting that SCUBE3 expression may serve as a potential diagnostic indicator in breast cancer." (PMID 34006286, 2021). "SCUBE3 expression may serve as a potential diagnostic indicator of breast cancer." (PMID 34006286, 2021). "To date, aberrant upregulation of SCUBE3 expression has been associated with unfavorable outcomes in various tumors, including NSCLC, breast cancer, metastatic melanoma, and osteosarcoma." (PMID 37237303, 2023). "In a recent study, the expression of SCUBE3 in breast cancer cells and tissues increased significantly, and its expression was high in primary glioma specimens but low in normal brains." (PMID 34980127, 2022). "Another study was performed in HER2-positive breast cancer, where it was discovered that SCUBE3 also demonstrated a tendency to be overexpressed." (PMID 35663937, 2022). "Then, we systematically evaluated SCUBE3 expression in a cohort of breast carcinoma samples collected for postoperative pathological diagnosis in a retrospective study." (PMID 34006286, 2021). "We found that the expression level of SCUBE3 was significantly upregulated in breast cancer tissue compared with adjacent normal tissues." (PMID 34006286, 2021). "Together, these results demonstrate that SCUBE3 is differentially expressed in breast cancer patients." (PMID 34006286, 2021). "We examined the expression levels of SCUBE3 in breast cancer using TIMER, UALCAN, and immunohistochemistry." (PMID 34006286, 2021). "In this study, we aim to explore and evaluate the prognostic values of SCUBE3 expression in breast cancer using clinical data of these patients and extensive bioinformatics data mining process." (PMID 34006286, 2021). "We analyzed the correlation between high expression of SCUBE3 and poor survival rate by multivariate Cox regression analysis, and proved that high expression of SCUBE3 can be used as an independent prognostic factor for breast cancer patients." (PMID 34006286, 2021). "Our findings in this study will help us enhance the understanding of the potentially positive role of SCUBE3 in breast cancer, and provide a theoretical basis for the early diagnosis, prognostic, and targeted therapy of breast cancer." (PMID 34006286, 2021). "We have comprehensively investigated the expression pattern of SCUBE3 in breast cancer and analyzed the proteins that interact with SCUBE3." (PMID 34006286, 2021). "Another important aspect of this study is that SCUBE3 expression is related to the clinical-pathological parameters of patients with breast cancer." (PMID 34006286, 2021).
breast carcinoma (continued). "To further examine the prognostic potential of SCUBE3 in breast cancer, we then analyzed the impact of SCUBE3 expression on the prognosis of breast cancer patients." (PMID 34006286, 2021). "Lastly, we analyzed the correlation of SCUBE3 expression and the prognosis of breast cancer, and demonstrated that SCUBE3 was an independent poor prognostic factor in breast cancer." (PMID 34006286, 2021). "Signal peptide-CUB-EGF domain-containing protein 3 (SCUBE3) is a secretory cell surface glycoprotein, which is rarely reported in breast cancer but has been overexpressed in a variety of other tumor tissues." (PMID 32322168, 2020). "Our study found that SCUBE3 also showed a trend of overexpression in Her2-positive breast cancer, and the related mechanism of its participation in this progression needs to be further explored." (PMID 32322168, 2020). "Since previous studies have shown that DEPDC1B promotes angiogenesis and metastasis of melanoma by competing with CDC16 to promote SCUBE3 secretion, we investigated whether a similar phenomenon exists in breast cancer." (PMID 37642235, 2023). "SCUBE3 is also an independent poor prognostic factor in breast cancer." (PMID 36142489, 2022). "We performed multivariate Cox regression analysis to investigate whether SCUBE3 expression may be an independent prognostic factor of breast cancer." (PMID 34006286, 2021). "To investigate whether the survival rate of breast cancer patients is related to the expression level of SCUBE3, we have investigated the correlation between SCUBE3 expression and survival rate of breast cancer patients using Kaplan–Meier analysis." (PMID 34006286, 2021). "We hypothesized that the possible oncogenic activity of SCUBE3 may impact the prognosis of breast cancer patients." (PMID 34006286, 2021). "Indeed, the survival status of high SCUBE3 expression group is persistently worse than that of low SCUBE3 expression group, which further supports the high SCUBE3 expression as an independent factor for the poor prognosis of breast cancer patients." (PMID 34006286, 2021). "Our data suggest that high SCUBE3 expression is correlated with high histologic grade and negative E-cadherin expression, which further support the important role of SCUBE3 in promoting breast cancer progression as well as its relationship with tumor metastasis and poor prognosis." (PMID 34006286, 2021). "Of the 137 breast cancer patients, 31 cases (22.6%) were identified as high SCUBE3 expression." (PMID 34006286, 2021). "The correlation between the expression of SCUBE3 and survival was calculated by multivariate Cox regression analysis to investigate whether SCUBE3 expression may be an independent prognostic factor of breast cancer." (PMID 34006286, 2021). "Therefore, understanding the regulation and molecular function of SCUBE3 may identify potential targets for the diagnosis and treatment of breast cancer." (PMID 34006286, 2021). "SCUBE3 expression was higher in TNBC in comparison to luminal, HER2+, and other breast-cancer subtypes." (PMID 36142489, 2022). "However, it is unclear whether and how SCUBE3 promotes breast cancer progression." (PMID 34006286, 2021). "What is more noteworthy is that there is no change of SCUBE3 expression in interference or overexpression of DEPDC1B in breast cancer cells in vitro." (PMID 37642235, 2023). "Likewise, SCUBE3 promotes breast cancer progression via the activation of TGF-β1/TWIST1 signaling, and its expression can also independently serve as an indicator of poor prognosis in breast cancer." (PMID 37237303, 2023). "The SCUBE3 expression does not affect the survival of breast cancer patients." (PMID 37642235, 2023). "Therefore, the close interaction between SCUBE3 and MMP-2/9 may suggest the role of SCUBE3 in the metastasis and progression of breast cancer, though future mechanistic studies are needed to verify this possibility." (PMID 34006286, 2021).
osteosarcoma (7 papers, 2020 to 2023). A usually aggressive malignant bone-forming mesenchymal neoplasm, predominantly affecting adolescents and young adults. "Malfunction of the SCUBE3 gene has been linked to problems such as craniofacial and dental defects, reduced body size, and defective endochondral bone growth in mice, and osteosarcoma in humans." (PMID 37662838, 2023). "SCUBE3 was also found to regulate glioma cell proliferation and promote proliferation of osteosarcoma cells, and its expression is correlated prognosis of patients with osteosarcoma." (PMID 37237303, 2023). "SCUBE3 also promotes the proliferation of osteosarcoma cells and influences the prognosis of patients with osteosarcoma." (PMID 34980127, 2022). "We also found that SEMA4D expression levels were inversely correlated to those of SCUBE3 in both GCTs and osteosarcoma samples from patients: higher levels of SEMA4D were found in osteoclast-rich samples in which SCUBE3 was low." (PMID 36138226, 2022). "SCUBE3 is highly expressed in osteosarcoma and non-small cell lung cancer, and SCUBE3 knockdown has been observed to inhibit the proliferation of cancer cells." (PMID 32764572, 2020). "In contrast, SCUBE3 mRNA levels were increased in post-denosumab-treated GCTs compared to untreated tumours and were also high in bone-forming osteoclast-poor osteosarcomas compared to osteoclast-rich osteosarcomas." (PMID 36138226, 2022). "Our data were consistent with most previous studies reported in other cancer types including NSCLC, osteosarcoma, and renal cell carcinoma, which suggested that high SCUBE3 expression may be a universal indicator of poorer prognosis in cancers." (PMID 34006286, 2021).
renal cell carcinoma (4 papers, 2021 to 2023). "Also, methylation of SCUBE3 is associated with significantly increased overall risk of death (P = 0.009) and cancer death or relapse (p = 0.0046) in patients with renal cell carcinoma." (PMID 37237303, 2023). "Erroneous hypermethylation of the promoter of SCUBE3 in renal cell carcinoma leads to a 45% reduction in the expression level of the gene as compared to control kidney cell expression levels." (PMID 37580336, 2023). "Using methylated DNA immunoprecipitation and whole-genome arrays combined with high-density expression arrays, the study showed that the promoter region of SCUBE3 is frequently methylated in primary renal cell carcinoma tumor samples (19% of examined cases)." (PMID 37237303, 2023). "In contrast to these apparent oncogenic functions, SCUBE3 might also serve as a tumor suppressor in the context of renal cell carcinoma." (PMID 37237303, 2023). "Genome wide approaches such as methylated DNA immunoprecipitation (MEDIP) and whole-genome array analysis, in combination with high-density expression analysis, identified SCUBE3 as a frequently methylated and silenced gene in renal cell carcinoma (RCC), and thus a candidate tumor suppressor gene." (PMID 36142489, 2022). "Besides these tumor-promoting functions of SCUBE3, genome-wide methylation analysis revealed that SCUBE3 is a tumor suppressor that may be epigenetically inactivated in renal cell carcinoma." (PMID 37237303, 2023).
cardiac hypertrophy (3 papers, 2016 to 2022). "Recently, SCUBE3 was found to be involved in cardiac hypertrophy in mice through TGFβ1-mediated transcriptional activation." (PMID 34980127, 2022). "Early studies have found that SCUBE3 can participate in cardiac hypertrophy in mice through transcriptional activation mediated by TGFβ1." (PMID 34980127, 2022). "SCUBE3 expression was observed in human cultured coronary smooth muscle cells and at low levels in the heart, and its overexpression led to cardiac hypertrophy in transgenic mice." (PMID 27815347, 2016). "SCUBE3 function is also associated with other tissues, for example, Scube3 overexpression in transgenic mice induced cardiac hypertrophy, and zebrafish Scube3 was recently identified as a key regulator of fast muscle development by modulating fibroblast growth factor signaling." (PMID 27815347, 2016).
glioma (3 papers, 2020 to 2023). A benign or malignant brain and spinal cord tumor that arises from glial cells (astrocytes, oligodendrocytes, ependymal cells). "Nevertheless, the function of SCUBE3 should be further explored in glioma, both in vitro and in vivo." (PMID 37237303, 2023). "In this study, SCUBE3 level was reduced by a new marine-isolated asterosaponin, which led to G1/S cell cycle arrest of glioma cells." (PMID 37237303, 2023). "Afterward, SCUBE3 protein was found to have high expression in primary glioma specimens from patients examined by immunohistochemistry but low expression in normal brain." (PMID 32764572, 2020). "However, little is known about the patterns of SCUBE3 expression and its potent mechanism in gliomas." (PMID 32764572, 2020). "There was little knowledge about SCUBE3 expression in gliomas." (PMID 32764572, 2020). "Because SCUBE3 expression levels in the test glioma cell lines follows the trend U251 > U87 > U373, and SCUBE3 overexpression rescued the inhibition of U251 induced by CN-3, the U251 cell line was selected to for further experiments to determine the underlying mechanisms of CN-3 treatment." (PMID 32764572, 2020). "Furthermore, secreted and/or cell-surface proteins like SCUBE3, in particular, should be examined in more glioma clinical samples, including tissue specimens, cerebrospinal fluid, and blood." (PMID 32764572, 2020). "In fact, to our best knowledge, there are no previous reports of any detrimental growth effects on glioma cell lines following SCUBE3 knockdown." (PMID 32764572, 2020).
hepatocellular carcinoma (3 papers, 2020 to 2025). A malignant tumor that arises from hepatocytes. "Together, these findings demonstrated that SCUBE3 promotes proliferation of hepatoma cells through CCNE1." (PMID 34980127, 2022).